YIPF4 (Yip1 domain family member 4)
Description:
Involved in the maintenance of the Golgi structure.
Synonyms: Nbla11189; MGC11061; FinGER4; YIPFalpha2
Tractability: Antibody: its Gene Ontology location is reachable by antibodies, with high confidence; UniProt predicts a signal peptide or a membrane-spanning region. PROTAC: ubiquitination databases record sites on it; its protein half-life has been measured.
Gene: Protein-coding gene on chromosome 2 (32,277,868 to 32,316,594, forward strand). Ensembl gene ENSG00000119820.
Subcellular location: Golgi apparatus, cis-Golgi network membrane
Subcellular location (Human Protein Atlas): Golgi apparatus; Plasma membrane; Vesicles
Gene Ontology:
Molecular function: protein binding
Biological process: endoplasmic reticulum to Golgi vesicle-mediated transport; vesicle fusion with Golgi apparatus
Cellular component: endoplasmic reticulum; Golgi apparatus; endomembrane system; membrane
Genetic constraint (gnomAD): Loss-of-function variants: 13 observed, 15.03 expected, observed/expected ratio (o/e) 0.86, 90% interval 0.56 to 1.37. The upper end of that interval is the gene's LOEUF score, 1.37, which puts it in group 5 of 6, group 1 being the genes least tolerant of losing a copy. Missense variants: 243 observed, 202.22 expected, observed/expected ratio (o/e) 1.2, 90% interval 1.08 to 1.34. Synonymous variants: 97 observed, 79.56 expected, observed/expected ratio (o/e) 1.22, 90% interval 1.03 to 1.44.
Homologues: Orthologues: chimpanzee YIPF4 (100% identical), macaque YIPF4 (99% identical), rabbit YIPF4 (99% identical), dog YIPF4 (99% identical), guinea pig YIPF4 (98% identical), mouse Yipf4 (98% identical), rat Yipf4 (98% identical), rat Yipf4l1 (97% identical), pig YIPF4 (95% identical), zebrafish yipf4 (85% identical), tropical clawed frog yipf4 (77% identical), Caenorhabditis elegans Y60A3A.19 (52% identical). Paralogues in human: YIPF5 (27% identical), YIPF7 (24% identical), YIPF6 (20% identical).
Diseases named in the same sentence as YIPF4 in open-access papers:
YIPF4 is named in the same sentence as 3 diseases in open-access papers, as found by Europe PMC text mining. Sharing a sentence is not in itself a finding about the gene and the disease.
YIPF4 shares sentences with these, for which no sentence is quoted: cervical cancer (1 paper); lymph node metastases (1); tumor (1).